ERBB2 (erb-b2 receptor tyrosine kinase 2)
Diseases named in the same sentence as ERBB2 in open-access papers (continued):
Sharing a sentence is not in itself a finding about the gene and the disease.
breast cancer (continued). "We previously showed using human breast cancer T47D and SUM190-PT cells that nectin-4 cis-interacts with ErbB2 and enhances its homo-dimerization and activation in a novel mechanism, activating the PI3K-AKT signaling and enhancing DNA synthesis." (PMID 33795719, 2021). "The median overall survival (OS) of stage IV breast cancer patients for the triple-negative and HER2/ERBB2-positive subtypes was approximately 1 year and 5 years, respectively." (PMID 34527584, 2021). "Furthermore, breast cancer database analysis of 35 genes in the canonical autophagy pathway shows that the upregulation of ATG12 and MAP1LC3B is associated with a low relapse-free survival probability of patients with ERBB2-positive breast tumors following treatments." (PMID 33801244, 2021). "In conclusion, we demonstrate herein that MIBC subtypes predict pathological response to NAC, indicating strong phenotypic similarities to breast cancer subtypes, including expression patterns of ESR1 and ERBB2." (PMID 34073233, 2021). "We found that ZFP36/TTP was phosphorylated mainly in breast cancer cell lines, including ERBB2-amplified SKBR3, and demonstrated that lapatinib—also ERBB2 siRNA-reduced the abundance of the phosphorylated ZFP36/TTP in a dose-dependent manner." (PMID 34535639, 2021). "These similarities indicate that subtyping of MIBC tumours based on mRNA analysis of ERBB2 and ESR1 expression has a clinical value in the prediction of pCR following NAC, as it is observed for breast cancer patients." (PMID 34073233, 2021). "Recent study revealed that ERBB2 promoted autophagy via upregulating the autophagy-related 12 (ATG12), which further induced resistance to ERBB2-targeted antibody lapatinib in breast cancer cells." (PMID 34252349, 2021). "We have measured and reported that the half-life of ErbB2 is ∼8 h in HEK293 cells and ∼9 h in breast cancer cells." (PMID 34725188, 2021). "The ErbB2-positive breast cancer cell line SKBR3, a widely used model to study ErbB2 expression, was chosen to assess the co-localization of SH3BGRL3 and ErbB2 proteins by confocal microscopy." (PMID 34380438, 2021). "Studies have shown that CHIP can ubiquitinate ErbB2 using u-BOX structure, thereby weakening the mitosis signaling pathway mediated by ErbB2 and ultimately inhibiting the proliferation of breast cancer." (PMID 33461174, 2021). "A breast cancer classification includes basal-like, luminal A or B, luminal ER−/AR+, and ERBB2/HER2-amplified." (PMID 34830320, 2021). "One in five women with breast cancer have an amplified transcript of ERBB2/neu oncogene and/or overexpression of growth-promoting protein HER2." (PMID 33670524, 2021). "A point-of-care mRNA STRAT4 breast cancer assay for ESR1, PGR, ERBB2, and MKi67, for use on the GeneXpert platform, has been recently validated on tissues from internationally accredited laboratories, showing excellent concordance with IHC." (PMID 34050358, 2021). "The human epidermal growth factor receptor (HER2)-positive (+) subtype, which accounts for 15–20% of all breast cancers, is defined by HER2 (ERBB2) gene amplification and/or protein overexpression." (PMID 34045483, 2021). "Clinicopathological variables such as tumor size, lymph node metastasis, histological grade, ER and PR expression, and HER2 status (also known as ERBB2), are prognostic and thereby drive decision making for breast cancer treatment." (PMID 33816299, 2021). "The ERBB2 gene (also known as human epidermal growth factor receptor 2 (HER2)) has a critical role in human malignancies, and in about 30 percent of breast cancers, it is exacerbated or overexpressed." (PMID 34307654, 2021). "The Xpert® Breast Cancer STRAT4* Assay (STRAT4)*, a standardized test for ESR1/PGR/MKi67/ERBB2 mRNA biomarker assessment, takes less than 2 hours." (PMID 33879115, 2021). "In breast cancer, CHIP targets human epidermal growth factor receptor 1 (Her2)/ErbB2, a member of the EGFR family, for degradation." (PMID 34831344, 2021).
breast cancer (continued). "Human epidermal growth factor receptor 2 (HER2/ErbB2) is a member of the epidermal growth factor receptor family, and HER2-positive (HER2+) breast cancer accounts for approximately 20% of the histological types of breast cancer with a poor prognosis." (PMID 34686673, 2021). "Mechanistically, fluorescence in situ hybridization, RNA immunoprecipitation, RNA pull-down and dual-luciferase reporter gene assays were conducted to confirm the interaction between circ-ERBB2 and miR-136-5p or miR-198 in HER2-positive breast cancer cells." (PMID 34732216, 2021). "However, the role and mechanism of circ-ERBB2 in HER2-positive breast cancer are still unknown." (PMID 34732216, 2021). "Those genes are frequently altered in different cancers, including AKT1, EGFR, KRAS, and STK11 in lung cancer and AKT1, BRCA2, ERBB2, and PIK3CA in Breast cancer." (PMID 34906079, 2021). "Based on the status of estrogen receptor (ER), progesterone receptor (PR) and receptor tyrosine-protein kinase erbB-2 (HER2), breast cancer is classified as Luminal A, Luminal B, HER2-positive (HER2-E) and triple-negative breast cancer (TNBC) subtypes." (PMID 34395234, 2021). "They convincingly showed that they detected clinically relevant GCN alterations (i.e., ERBB2, EGFR, MET) for n = 14 breast cancer samples using the matched normal samples or a normal reference pool." (PMID 34638507, 2021). "Genes including hTERT, HER2 (ERBB2), HRAS, KRAS and c-MYC confer increased proliferative capacity in breast cancer." (PMID 34988459, 2021). "It is known from breast cancer that ERBB2 overexpressing tumours respond well to chemotherapy, especially in combination with a taxane-based agent and an anti HER2-antibody, currently being the established neoadjuvant chemotherapy regime." (PMID 34073233, 2021). "In breast cancer, ECD protein is overexpressed and its overexpression is correlated with shorter survival, particularly in ErbB2-overexpressing patients." (PMID 33941617, 2021). "ErbB2/HER2 has received particular attention, its amplification/overexpression having defined a genomic subtype of breast cancer and inspired a generation of HER2-targeted therapies." (PMID 33669586, 2021). "We detected unmethylated CpG islands in the promoter regions of the ERBB2 and PGR genes, which are used in the classification of breast cancer subtypes." (PMID 34527193, 2021). "Strikingly, ERBB2 and GRB7—chromosomally co-localized with ERBB2 and known to be frequently co-amplified with it in HER2-amplified breast cancer —are the two most significantly downregulated genes in the kinase+PTENloss group when compared to wildtype samples." (PMID 34344439, 2021). "The ErbB2 (also known as EGFR2 and HER2) is a widely studied antigen in early breast cancer diagnosis." (PMID 34577374, 2021). "Breast cancer is commonly separated into Luminal A (LumA), Luminal B (LumB), epidermal growth factor receptor ERBB2/HER2-overexpressing (HER2+), and basal epithelial-like (BL) based on gene expression profiles." (PMID 33574966, 2021). "In this study, we demonstrated that ERBB2 promotes autophagy by increasing the protein levels of the autophagy gene ATG12 (autophagy-related 12), contributing to the resistance of breast cancer cells to chemotherapy drugs or ERBB2-targeted antibody treatments." (PMID 33801244, 2021). "Triple-negative breast cancer (TNBC) is characterized by the lack of expression of the estrogen receptor (ER), progesterone receptor (PR), and human epidermal growth factor receptor 2 (ERBB2/HER2) and is often a basal-like breast cancer." (PMID 34356858, 2021).
breast cancer (continued). "Breast cancer (BC) is a heterogeneous disease that is classified into different subtypes depending on the expression of the estrogen and progesterone receptors and the amplification of human epidermal growth factor receptor 2 (HER2/ERBB2)." (PMID 34249678, 2021). "Interestingly, the fusion genes identified by analyzing breast cancer genome rearrangements indicated that ErbB2 might serve as an adaptor for DEPTOR in regulating the mTOR pathway 25, thus adding another layer of complexity in the cross-talk between DEPTOR and ErbB2 in breast tumorigenesis." (PMID 33995662, 2021). "The previous result found that ERBB2 (or HER2) can be cleaved by proteases, such as ADAM10, in HER2-overexpressing breast cancer cells." (PMID 33947097, 2021). "ECD cleavage of ERBB2 generates membrane-bound ERBB2 fragment, which can mediate the growth and survival of HER2-overexpressing breast cancer cells." (PMID 33947097, 2021). "Abnormal expression of human epidermal growth factor receptor 2 (HER2, also known as ErbB2) is present in 15–20% of all breast cancers." (PMID 34095130, 2021). "HER2 (EGFR2,ERBB2) amplified in approximately 18–25% of human breast cancers requires homodimerization or heterodimerization followed by autophosphorylation in order to be activated." (PMID 33637115, 2021). "However, whether DEPTOR regulates the growth of ErbB2-positive breast cancer cells remains unknown." (PMID 33995662, 2021). "Evaluation of HER2 (ERBB2, neu) status has also been routinely used in breast cancer molecular diagnostics since the end of the 1990s." (PMID 34408238, 2021). "Similarly, HER2-targeted therapy may be applied to other cancer types analogous to breast cancer because ERBB2/HER2, which can be amplified in breast cancer, is also mutated and/or amplified in subsets of glioblastoma and gastric, serous endometrial, bladder and lung cancers." (PMID 34869372, 2021). "Taken together, Xpert® Breast Cancer STRAT4 mRNA testing for ESR1, PGR, ERBB2, and MKI67 demonstrated good performance when compared to the diagnostic gold standard IHC/ISH." (PMID 34572945, 2021). "EphB6 signaling, known to suppress breast cancer cell aggressiveness by interacting with EPHB4 and interfering with EPHB4 action, was repressed by Pparγ1 in ErbB2 mammary tumors." (PMID 33946495, 2021). "However, the upregulation of autophagy by ERBB2 expression in cancer may provide a therapeutic window for cancer where autophagy can be targeted as it is demonstrated in this study that ERBB2 antibody inhibited autophagy to sensitize ERBB2-positive breast cancers to chemotherapy drugs." (PMID 33801244, 2021). "Authors found that upon ErbB2/ErbB3 dimerization, the RTK phosphorylate ErbB2PPPI3K recruits PI3K for degradation and suppresses AKT activation in MCF7 breast cancer cells." (PMID 33809714, 2021). "According to the expression pattern of biomarkers, including estrogen receptor (ER), progesterone receptor (PR) and human epidermal growth factor receptor 2 (HER2, also known as Neu, ErbB2, EGFR2), breast cancer can be classified into several subtypes." (PMID 34267653, 2021). "The input features are the corresponding genes of well-established breast cancer biomarkers (ESR1, PGR, ERBB2, MKI67, PLAU) and the hybrid ensemble approach's final selected genes." (PMID 34290286, 2021). "When we next applied the model on 712 breast cancer whole-slide tissue images from the FinHer dataset (external test set), the CNN predicted ERBB2 status with an AUC of 0.67 (95% CI, 0.62–0.71) and an AP of 0.37 (95% CI, 0.32–0.44) with a baseline AP of 0.23." (PMID 33597560, 2021).
breast cancer (continued). "These included pathways mediating tumor cell proliferation, survival, and invasion as well as several essential molecular pathways that are known to be critical for the pathophysiology of ER+ breast cancers, in particular, the ESR1 and ERBB2 pathways." (PMID 34524841, 2021). "About 20% of breast cancers are driven by amplification of the ERBB2 gene and overexpression of its gene product, the HER2 protein." (PMID 33907275, 2021). "In breast cancer, HOXB5 enhanced cell growth and invasion partly through RET, ERBB2, EGFR, and ESR1." (PMID 34440097, 2021). "The GRB7 gene is located in close proximity to the HER-2/erbB2 gene, forming the HER-2-amplicon core, and is commonly, though not always, co-amplified and overexpressed with HER-2 in human breast cancers." (PMID 32595827, 2020). "There are three subtypes of breast cancer depending on the presence of 3 receptors for estrogen (ER), progesterone (PgR) and human epidermal growth factor (ERBB2/HER2)." (PMID 32922387, 2020). "Another example is trastuzumab, which is a humanized antibody directed against HER2 (also known as ERBB2) and which is overexpressed in 15–20% of breast cancers." (PMID 33198152, 2020). "Neuregulin is a ligand for ErbB3, and its presence leads to ErbB2 and ErbB3 heterodimerization, resulting in reduced cytotoxicity of T-DMI in breast cancer cell lines." (PMID 33081383, 2020). "This study was caried out in human breast cancer cell lines (MDA-MB-468, KPL4 and SK-BR-3) by measuring the expression of EGF, ErbB2, andIGF-1 biomarkers." (PMID 33276535, 2020). "Trastuzumab also upregulated PERP in EVs emitted by trastuzumab-sensitive breast cancer cells MCF7/Her2-18, a derivative of human breast tumor cells MCF7 producing exogenous ErbB2." (PMID 33023655, 2020). "For example, the presence of genomic alterations in genes such as ERBB2, PIK3CA, AKT1, ESR1 and NTRK in advanced breast cancer patients help to stratify patients for targeted therapies." (PMID 33167363, 2020). "In the breast cancer cell line SKBR3, over-expression of miR-125a down-regulates ErbB2 and ErbB3 at both the transcript and protein level, thereby reducing the cells' migration and invasion capabilities." (PMID 32185126, 2020). "Our observation that overexpression of miR-125a-3p in a cell line of the basal-like breast cancer subtype resulted in high expression of ErbB2 prompted us to further explore whether modulation with miR-125a-3p may sensitize these cells to the highly effective anti-HER2 therapies." (PMID 32185126, 2020). "Belonging to the Epidermal Growth Factor Receptor (EGF/EGFR) family, the ERBB2/Human Epidermal Growth Factor Receptor 2 (HER2) receptor signaling pathway has a well-documented role in driving aggressive, metastatic breast cancers when aberrantly activated." (PMID 33172038, 2020). "Recently, the histological resemblance of SDC to breast cancers has led to the study of HER2 (human epidermal growth factor receptor 2, also known as ERBB2) expression." (PMID 33692941, 2020). "Along with ERBB2, MEMO1 was identified to complex with Phospholipase C γ (PLCγ )—an additional signaling molecule downstream of activated ERBB2—in breast cancer cells treated with HRG." (PMID 33172038, 2020). "Breast cancer cells were chosen on the basis of their estrogen (ER), progesterone (PR), and ERBB2 (HER2) receptor assets, in order to simulate a differential response to RT between triple negative breast and luminal adenocarcinomas." (PMID 33080870, 2020).
breast cancer (continued). "Using a panel of five breast cancer cell lines with ErbB2 overexpression, we explicitly demonstrated that HSP90 inhibitor induced the endocytosis and lysosomal degradation of ErbB2, which are accompanied by the ubiquitylation of ErbB2." (PMID 32327714, 2020). "Analyzing the expression of estrogen receptor (ER), progesterone receptor (PR), and epidermal growth factor receptor 2 (ERBB2, NEU or HER2) is still the basis for breast cancer stratification and an important determinant of breast carcinoma cell phenotype." (PMID 32854355, 2020). "MEDICA treatment is shown here to suppress ErbB2 breast tumors and lung metastasis in ErbB2/neu MMTV transgenic mice, to suppress ErbB2/neu xenografts in nod/scid mice, and to suppress survival of AU565 and BT474 human ErbB2 breast cancer cells." (PMID 32695336, 2020). "Lapatinib is a small molecule inhibitor that can block several tyrosine kinase receptors' phosphorylation (EGFR, ErbB2, Erk1/2, and AKT kinases) and is generally used for advanced breast cancer therapy." (PMID 33425217, 2020). "These second-generation inhibitors irreversibly inhibit both EGFR and ErbB2 and have shown potency against HER2+ breast cancer." (PMID 32366937, 2020). "Breast cancer is classified into at least four subtypes (luminal A, luminal B, human epidermal growth factor receptor 2 (HER2)/erythroblastic oncogene B 2 (ErbB2)-enriched, and basal-like) based on gene expression patterns." (PMID 32486413, 2020). "Around 15–20% of all breast cancers overexpress the HER2 receptor, many of them due to the amplification of the ERBB2 gene on chromosome 17, and HER2-driven cancers are generally aggressive." (PMID 31992741, 2020). "Next, we compared the BRF2 Outlier results to known breast cancer biomarkers, HER2 (ERBB2), MYC, PIK3CA, and ER (ESR1) using the same stringent threshold criterion." (PMID 33176745, 2020). "SKBR3 breast cancer cells were grown on microchips, transformed to express an actin-green fluorescent protein (GFP) fusion protein, and ErbB2 was labeled via an Affibody in a two-step procedure with a quantum dot (QD) nanoparticle." (PMID 32714928, 2020). "A role of alcohol has been well recognized in initiation and progression of breast cancer, presumably via multiple cellular and molecular mechanisms, including the EGFR/ErbB2 pathways." (PMID 31605532, 2020). "Correspondingly, ErbB2 targeting has proved an effective approach in the battle against ErbB2-positive breast cancers, and current therapies approved by the FDA include ErbB2-directed antibodies and small molecule tyrosine kinase inhibitors." (PMID 32327714, 2020). "HER2, also named ErbB2, belongs to the epidermal growth factor receptor (EGFR) family, and is overexpressed in 20–30% of breast cancer cases." (PMID 32511274, 2020). "In order to investigate this detected mRNA expression, we compared the ERBB2, ESR1, and PGR mRNA expression in available TCGA breast cancer samples and grouped the expression values by the annotated result of the immunohistochemistry (IHC) assay." (PMID 32793490, 2020). "MiR-125b has been found to constrain breast cancer cell proliferation, invasion and migration by targeting erythropoietin (EPO) and EPO receptors and ERBB2 25-27." (PMID 32328182, 2020). "TAAs identified in breast cancer include HER2, CEA, hepatocyte growth factor receptor (c-Met), NKG2D and ErbB2+MUC1." (PMID 32899932, 2020). "Suppression of ErbB2 cell growth and survival by MEDICA was further verified in mouse RH2111 ErbB2/neu cells and human breast cancer cell lines AU565 and BT474 that overexpress ErbB2." (PMID 32695336, 2020). "Human epidermal growth factor receptor 2 (HER2)-positive breast cancers are effectively managed by a combination of anthracyclines (e.g., DOX) and trastuzumab (Trz), a humanized anti-HER2/ErbB2 drug." (PMID 32604861, 2020).